HSPA6 (heat shock protein family A (Hsp70) member 6)
Diseases named in the same sentence as HSPA6 in open-access papers (continued):
Sharing a sentence is not in itself a finding about the gene and the disease.
cancer (continued). "Low levels of HSP90AB1/TRAP1, HSPA6/TRAP1, and HSP90AA1/TRAP1 in urine increase the probability of the patient having cancer, whereas low levels of CCT2/HSP90AB1 and HSPB1*HSPA9 in urine are strongly associated with non-cancer groups." (PMID 34692733, 2021). "The association of IER5 and HSPA6 expression with cancer progression may be related to the in vitro observation that IER5 and HSF1 are required for the proliferation of cancer cells under stressed conditions." (PMID 26754925, 2016). "MTCH2 and HSPA6 play various roles in different cancers but have not been associated with CRC." (PMID 35459861, 2022). "Among these, PLXNA3, HLA-E, DDX58, IKBKE, HSPA6, SOS2, and HSPA1A stood out, with significantly elevated expression levels in LIHC compared to other cancer types." (PMID 39000042, 2024). "HSPA6 and HSPA7 are family members of the HSP70 proteins, which are abundantly present in cancer and play crucial roles in cancer development, progression, and metastasis, clinically resulting in diverse outcomes for patient survival." (PMID 36855205, 2023). "We analyzed the methylation status of these genes in TCGA database and found the methylation of SHE, HSPA6 and FGF8 were lower in normal tissue then cancer tissue." (PMID 29029430, 2017). "Moreover, metformin upregulated the mRNA expression of numerous genes, including heat shock protein family A (Hsp70) member 6 (HSPA6), a cancer immune-related gene." (PMID 38474224, 2024). "We counted the numbers of pathways affected by each HSP; the results suggested that HSPA1L, HSPA12B, HSPA6, HSPA7 and HSPA12A may influence the activity of most cancer-related pathways and thus potently affect tumor development." (PMID 34712697, 2021). "This included HSPA6, which is not upregulated in cancer cells addicted to HSF1, but is strongly upregulated during a bona fide heat shock response." (PMID 24516381, 2014). "Moreover, each physicochemical component of CAP regulated a unique set of genes wherein the non-ROS constituents of CAP targeted HSPA6 and PTGER3, which showed anti-proliferative and pro-apoptotic activity in the cancer cells." (PMID 32947888, 2020).
tumor (36 papers, 2011 to 2026). "A dual immunofluorescence labelling assay provided further evidence that BARX1 was overexpressed and associated with HSPA6 overexpression in OS tumour tissue." (PMID 36927457, 2023). "The IF assay indicated that BARX1 was overexpressed and associated with HSPA6 overexpression in OS tumour tissues, which revealed the regulatory effect of BARX1 on HSPA6 from a clinical perspective." (PMID 36927457, 2023). "HSPA6 were significantly upregulated in the GC tissues compared to the normal stomach epithelium and were associated with Ming classification (p < 0.001) and tumor size (p = 0.002)." (PMID 36458368, 2023). "Tumor NK cells expressed similar DEGs to tumor T cells and were enriched for genes associated with protein folding and cytokine expression, including genes coding for heat shock proteins HSPA6, HSPA1B, and HSPA1A, and IFNG, a common cytotoxic marker." (PMID 35534852, 2022). "In the CRC tumor group, the expression levels of HSPA6 and NOTCH3 protein were dramatically up-regulated, while GPD1L, PKP2, and SMAD9 protein were dramatically down-regulated (all P < 0.05)." (PMID 40796704, 2025). "Although there are limited functional studies of HSPA6 in stem cells, our findings parallel those in tumor cells, where HSPA6 is crucial for cell proliferation and survival." (PMID 40313859, 2025). "The HSPA6, a heat shock protein family A (Hsp70) member 6, a tumor suppressor that inhibits proliferation, migration and invasion of BT549 cells, is regulated by Thymoquinone." (PMID 38686052, 2024). "The expression of HSPA6 was significantly correlated with tumor size (p = 0.002) and Ming classification (p < 0.001) but not with age, gender, tissue grading and N‐phases (p > 0.05)." (PMID 36458368, 2023). "Consistent with this in vivo assay, mouse tumor models showed that the weight of the HSPA6‐knockdown XGC‐1 cells (0.40 ± 0.28 g) was significantly lower than that of the respective controls (1.72 ± 0.77 g)." (PMID 36458368, 2023). "In all, this study would reveal HSPA6 is a novel prognostic biomarker and promotes tumor progression in GC." (PMID 36458368, 2023). "The effects of HSPA6 on GC proliferation were performed by EdU assay in vitro and mouse tumor models in vivo." (PMID 36458368, 2023). "In contrast, tumor T cells’ DEGs coded for heat shock proteins, such as HSPA6, HSPA1A, and HSPA1B in addition to genes related to T cell development and function, such as NR4A1 and NR4A2." (PMID 35534852, 2022). "HSPA6 expression was positively associated with immune score, stromal score, and ESTIMATE score, but negatively correlated with tumor purity." (PMID 35281087, 2022). "In view of the obligatory function of genomic variation in immune cell infiltration and tumor immunoregulation, CNV and somatic mutation were used to identify distinguishing genomic alterations in the subgroups showing differential HSPA6 expression." (PMID 35281087, 2022). "The result also indicated that HSPA6 was closely related to tumor cell immunity, proliferation, and apoptosis, such as antigen processing and presentation and PI3K-AKT signaling pathways (only top ten)." (PMID 35281087, 2022). "When comparing the three cohorts, we found that the subgroup with low expression levels of HSPA6 was closely related with tumor metabolism-related mechanisms, such as beta-alanine, pyruvate and propanoate metabolism." (PMID 35281087, 2022). "Taken together, these studies strongly demonstrated the inhibitory effects of HSPA6 on tumor cell growth, migration and invasion." (PMID 34017687, 2021). "Most likely, ARHGEF10L overexpression promoted tumor cell proliferation, migration, and invasiveness to stimulate HSPA6 expression, although the exact function of HSPA6 in tumorigenesis is not well known." (PMID 33833821, 2021). "Similarly, in the LUAD tumor group, HSPA6, NOTCH3, and PKP2 protein expression were dramatically stimulated, whereas GPD1L and SMAD9 protein expression were dramatically suppressed (all P < 0.05)." (PMID 40796704, 2025).
tumor (continued). "Real‐time PCR was used to verify the expression of HSPA6 mRNA in the tumour tissues." (PMID 39716349, 2025). "CCNL1, SOCS3, and HSPA6, which are highly expressed in patients with ccRCC, may promote tumor generation." (PMID 37293297, 2023). "Although HSPA6 plays an important role in various tumours, whether HSPA6 can affect the progression of OS remains unclear." (PMID 36927457, 2023). "HSPA6 can directly or indirectly inhibit or promote tumour occurrence and development." (PMID 36927457, 2023). "In vivo mouse tumor models were performed to evaluate the effects of HSPA6 on GC growth." (PMID 36458368, 2023). "We also found that HSPA6 was closely correlated with genomic variations and tumor microenvironment." (PMID 35281087, 2022). "HSPA6 is considered an important tumor-related gene under the control of ARHGEF10L." (PMID 33833821, 2021). "Increased expression of endoplasmic reticulum stress-induced transcripts such as PPP1R15A (GADD34), heat shock proteins HSPA6 and DNAJB1, and the stress-related transcription factor DDIT3 were observed in BRAFMT tumours with the highest-risk of disease relapse." (PMID 29568398, 2018). "Indeed, knocking down HSPA6 suppressed cell proliferation in vitro and tumor growth in vivo." (PMID 36458368, 2023). "After carefully analyzing, the HSPA6 gene, as the highly significantly upregulated gene and involved into multiple pathways by TQ treatment, was captured by us, and previous studies showed that this gene might be related to tumor repression." (PMID 34017687, 2021). "Furthermore, we found a novel role of HSPA6 functioning as a potentiation regulator in the GE-mediated anti-tumor effect, which suggests a capability of prognostic marker for enhancing the GE-induced anti-tumor effects." (PMID 28187175, 2017). "First, our study showed that naïve T-cells in tumor tissues exhibit increased expression of HSPs, including HSPD1, HSPE1, HSPA1A, HSPA6, and DNAJB1." (PMID 41186645, 2026). "Meanwhile, when compared with normal group, the HSPA6, NOTCH3 and PKP2 expression were significantly increased in LUAD tumor group, but GPD1L and SMAD9 expression were dramatically decreased in control group (all P < 0.001)." (PMID 40796704, 2025). "The expression of heat-shock protein-related genes such as HSPA6,HSPA1B, and HSPA1A equips this macrophage subset to cope with the stressful tumor microenvironment and play a role in immune regulation." (PMID 41394809, 2025). "Compared to the control group, serum levels of HSPA6 and NOTCH3 were significantly elevated in the CRC tumor group, whereas GPD1L, PKP2, and SMAD9 exhibited a marked decrease." (PMID 40796704, 2025). "Among these subpopulations, the proportions of CFD+ iCAFs, HSPA6+ mCAFs, and HLA-DQA1+ apCAFs were markedly elevated in CRCM, potentially correlating with tumor metastasis." (PMID 40225580, 2025). "Conversely, the genes FTH1, SQSTM1, HSPA6, TSPYL2, PHLDA2, ITGAX, and DNAJA4 are expected to act as versatile protein regulators, potentially suppressing tumor cell genetic instability and promoting autophagy, apoptosis, and other forms of cell death." (PMID 40986633, 2025). "The result demonstrated a significant increase in HSPA6 and NOTCH3 expression, but a significant decreased in GPD1L, PKP2 and SMAD9 in CRC tumor group when compared to those in normal group (all P < 0.001)." (PMID 40796704, 2025). "The results showed that, compared to normal samples, HSPA6 and NOTCH3 were dramatically increased, while GPD1L, PKP2, and SMAD9 were dramatically decreased in tumor samples in both the CRC training dataset and the CRC validation dataset (all P < 0.05)." (PMID 40796704, 2025).
tumor (continued). "All six amplifications that led to a substantial increase in expression in tumor samples were also reported as up-regulated HSP when comparing normal and tumor tissues (CCT3, HSPA6, DNAJA3, TRAP1, DNAJC5, and DNAJC5B)." (PMID 38816397, 2024). "Whereas JUN, HSPH1, HSPA8, HSPA6, HSP90AB1, and EGR1 were found to be the DEGs in both Tumor vs. normal and tumor vs. metastasis group." (PMID 37335089, 2023). "The higher the expression level of HSPA6, the higher the immune score, stromal score, and ESTIMATE score; the opposite effect was observed for tumor purity." (PMID 35281087, 2022). "Although our data has demonstrated the importance of the HSPA6 in GE-treated EJ cells, additional studies should be performed to clearly elucidate the relationship between other HSP family molecules and the anti-tumor effect of GE." (PMID 28187175, 2017). "The elevated expression of HSPs such as HSPD1, HSPE1, HSPA1A, HSPA6, and DNAJB1 suggests that naïve T-cells in tumor tissues may be under a state of stress or heat shock." (PMID 41186645, 2026). "Moreover, compared to normal samples, HSPA6, NOTCH3, and PKP2 were dramatically overexpressed, while GPD1L and SMAD9 were dramatically de-expressed in tumor samples in both the LUAD training dataset and the LUAD validation dataset (all P < 0.05)." (PMID 40796704, 2025). "Notably, some genes (e.g., MET, HSPA6, ID1, MECOM, POU2AF1, SFRP4, CDH1) exhibited expression predominantly in tumor cells and a limited number of other cell types." (PMID 40954493, 2025). "In addition, the expression of serum HSPA6, NOTCH3 and PKP2 were significantly up-regulated in the LUAD tumor group, while GPD1L and SMAD9 showed a significant down-regulation trend when compared to the control group." (PMID 40796704, 2025). "For example, the HSPA6 protein is upregulated during thermal heat stress, but not during tumor progression." (PMID 36980299, 2023). "Indeed, inducible members of the HSP gene family, namely heat shock 70 kDa protein 6 (HSPA6) followed in rank by HSPA1A and HSPA1B were the most dominantly induced genes 4 h after PDT in the human tumor cell lines." (PMID 21738796, 2011). "Finally, comprehensive analyses revealed significant differences in genomic variation, tumor-infiltrating immune cells (TIICs), different tumor microenvironments (TMEs), immune checkpoint (ICP) expression levels, when compared between patients with low and high expression levels of HSPA6." (PMID 35281087, 2022). "Finally, while the five biomarker proteins (HSPA6, NOTCH3, PKP2, SMAD9, and GPD1L) are primarily intracellular, their presence in serum could potentially be attributed to tumor derived extracellular vesicles or cell lysis during tumor progression." (PMID 40796704, 2025).
infection (11 papers, 2008 to 2025). The state of being infected such as from the introduction of a foreign agent such as serum, vaccine, antigenic substance or organism. "Anti-apoptotic factors including serine protease inhibitors (SERPINB10, SERPINA3–8 (Serpin domain-containing protein, LOC106504547), and SERPIN11A) and heat shock proteins (HSP70.2 and HSPA6), were only found after infection with swH1N1 compared to control." (PMID 39247193, 2024). "Here we report that an additional HSP70 member, HSPA6, was induced and reached to a peak at 6 h post infection (hpi)." (PMID 34025620, 2021). "The IRES-Luc activity was reduced comparably in HSPA6-depleted cells in the presence or absence of EV-A71 infection, suggesting that HSPA6 facilitated the IRES activity of EV-A71 through chaperoning cellular proteins rather than viral proteins." (PMID 34025620, 2021). "In summary, we demonstrated not only that HSPA6 was induced during EV-A71 infection to facilitate its IRES-mediated translation, but also that it played roles in the IRESs from other viruses." (PMID 34025620, 2021). "The results showed that in the absence of EV-A71 viral proteins, comparable patterns of reduction in IRES-mediated luciferase activity were found in both HSPA6 knockdown and HSPA6 KO cells as those in the presence of EV-A71 infection." (PMID 34025620, 2021). "We transfected HSPA6 KO RD cells with a small amount of HSPA6-expressing plasmid (0.2 μg/6 × 105 cells) to restore HSPA6 expression close to its endogenous levels before EV-A71 infection (compare lanes 1 and 4)." (PMID 34025620, 2021). "To understand the importance of this induction, we infected RD cells with a lentivirus carrying the shRNA specific to HSPA6, followed by EV-A7 infection 48 h post lentivirus transduction." (PMID 34025620, 2021). "In this study, HSPA5, HSPA1B, HSP90B1 and HSPA6 were up-regulated at 24 hpi to various degrees following CPIV3 -infection of MDBK cells." (PMID 31101113, 2019). "In HIV-2 infected PBMC only HSPA6 gene was differentially up regulated on day 15 post-infection compared to HIV-1 infected PBMC that was consistent with the microarray and day 7 real-time PCR results." (PMID 26821323, 2016). "The HSPA6 gene (coding for heat shock protein, Hsp70) was significantly overexpressed in the B. bigemina virulent-strain-infected group, which presented the highest increase in rectal temperature during experimental infection." (PMID 39859202, 2025). "More importantly, it also restored these three infection indices in HSPA6 KO RD cells." (PMID 34025620, 2021). "The importance of these results lies in the validation of TFF1, GSTA5, HSPA6, FOS, MPIG6B, F2 and HP not only as key markers for the presence of infection but also for their specificity in differentiating between various Mpox strains." (PMID 39456924, 2024). "We reported that HSPA6 was induced by EV71 infection and involved infection in both RD cells and neurogliocytes." (PMID 35308396, 2022). "Genes in group E were slightly up-regulated as early as 8 hpi during infection; some heat shock proteins, such as HSPB1, HSPA6, HSPA1B were found in this group." (PMID 18811943, 2008). "Results showed that the inducible effect of EV71 infection on HSPA6 and other three heat shock proteins was not significant when detection was performed at 8 h post-infection (hpi)." (PMID 35308396, 2022). "Results showed that silencing of HSPA6 did not affect the infection of CVA6, CVA10, CVA16, and CVB1-3, which was different from the observation for EV71 infection." (PMID 35308396, 2022). "Our preliminary data indicated that the HSPA6 mRNA levels were greatly induced after EV-A71 infection (data not shown), suggesting that EV-A71 upregulated HSPA6 at least at the transcription level." (PMID 34025620, 2021).
infection (continued). "Among them, the expression of 9 genes, such as heat shock protein family A (Hsp70) member 6 (HSPA6), lectin, galactoside-binding, soluble, 15 (LGALS15), and complement factor I (CFI), were significantly enhanced by infection in both R lines when compared to their respective S lines." (PMID 30678719, 2019).
neurodegenerative disease (6 papers, 2017 to 2022). A disorder of the central nervous system characterized by gradual and progressive loss of neural tissue and neurologic function. "HSPA6 plays an important role in research on neurodegenerative diseases, tumors, biosensors, and other topics." (PMID 35205234, 2022). "HSPA6 was also shown to be expressed at high levels in neurodegenerative diseases and in tissue or cells under oxidative stress." (PMID 36046596, 2022). "Becirovic and Brown (2017) illustrated that HSPA6 is involved in the post-stress transcriptional recovery in neurodegenerative diseases." (PMID 35531067, 2022). "It was also found that HSPA6 has previously been examined in human neurodegenerative diseases and was proposed as a potential treatment strategy to counter PD." (PMID 29653596, 2018). "Interestingly, the HSPA6 gene is found in the human genome but not in mouse and rat, hence it is absent in current animal models of neurodegenerative diseases." (PMID 28484369, 2017). "To advance knowledge of HSPA6, we investigated whether it is targeted to stress-sensitive neuronal sites with components of a protein disaggregation/refolding machine in human neuronal SH-SY5Y cells that have been previously used as a model in studies of neurodegenerative diseases." (PMID 28484369, 2017). "The HSPA6 gene is present in the human genome, and in the marmoset monkey (NCBI gene ID: 100411854), camel and goat but is not found in the genomes of mouse and rat, hence it is absent in current animal models of neurodegenerative diseases." (PMID 28484369, 2017).
kidney disease (1 paper, 2023). "Other studies have indicated that HBB, HSPA6, and NFKBIZ may play essential roles in kidney disease." (PMID 37293297, 2023).